PCSK6 (proprotein convertase subtilisin/kexin type 6)
Diseases named in the same sentence as PCSK6 in open-access papers (continued):
Sharing a sentence is not in itself a finding about the gene and the disease.
glioma (2 papers, 2021 to 2023). A benign or malignant brain and spinal cord tumor that arises from glial cells (astrocytes, oligodendrocytes, ependymal cells). "PCSK6 has been confirmed as candidate gene of glioma cell invasion, which can be circumscribed by abatement of PCSK6." (PMID 34301174, 2021).
hepatocellular carcinoma (2 papers, 2015 to 2022). A malignant tumor that arises from hepatocytes. "PCSK6 was identified from human hepatoma cells based on sequence similarities to other subtilisin-like proteases." (PMID 36362216, 2022).
inflammatory bowel disease (2 papers, 2023 to 2024). A spectrum of small and large bowel inflammatory diseases of unknown etiology. "For instances, in inflammatory bowel disease (IBD) research, proprotein convertase subtilisin/kexin type (PCSK6) has been implicated in increasing the proportions of Th1 cells and M1 macrophages, both of which are critical for effective immunotherapy." (PMID 39906740, 2024). "This study was aimed at investigating the expression and role of proprotein convertase subtilisin/kexin type (PCSK6) in inflammatory bowel disease (IBD)." (PMID 37211384, 2023). "It was discovered in inflammatory bowel disease (IBD) research that, PCSK6 expression increases in IBD, meanwhile, PCSK6 is closely related to the increased proportion of Th1 cells." (PMID 37211384, 2023).
prediabetes (2 papers, 2022 to 2025). "Gene-based analysis also identified PCSK6 gene that was associated with prediabetes status change." (PMID 35769078, 2022).
allergic asthma (1 paper, 2019). A asthma with a basis in a pathological type I hypersensitivity reaction. "Namely, for environment IgE sensitization (METTL1), for allergic asthma (NTRK1), and several for FeNO (MAP3K14, NTRK1, FBXL7, PCSK6, SLC9A3, CDH26, CAPN14, and MAP3K14)." (PMID 31300640, 2019).
amenorrhea (1 paper, 2022). The absence of menses in a woman who has achieved reproductive age. "In human genetic studies, GDF9 and BMP15 variants are found in women with premature ovarian failure and amenorrhea, suggesting that GDF9 and BMP15 could be potential PCSK6 substrates in the ovary." (PMID 36362216, 2022).
anemia (1 paper, 2020). A reduction in the number of red blood cells, the amount of hemoglobin, and/or the volume of packed red blood cells. "PCSK6 (involved in iron homeostasis) may be associated with the evolutionary response to anemia in Sheko cattle." (PMID 33287320, 2020).
aneurysm (1 paper, 2020). Bulging or ballooning in an area of an artery secondary to arterial wall weakening. "The risk for development of aortic dissection and aneurysms is increased in patients with genetic diseases resulting in a defective TGFB-signaling, where PCSK6 is one of the key proteases involved in the TGFB1 axis." (PMID 32325687, 2020).
aortic aneurysm disease (1 paper, 2020). "Human genetic variants in the PCSK6 locus have been linked with increased blood pressure and aortic dissection, which are both known to be associated with aortic aneurysm formation." (PMID 32325687, 2020). "However, whether an altered expression of PCSK6 would be associated with aortic aneurysm disease remains to be further investigated." (PMID 32325687, 2020).
atrial septal defect (1 paper, 2022). Interauricular communication is a congenital malformation characterized by a communication between the atrial chambers of the heart. "Moreover, a PCSK6 variant is found in a Spanish family with atrial septal defects and interatrial septal aneurysm." (PMID 36362216, 2022).
bladder cancer (1 paper, 2022). "However, the potential contribution of frequently altered ASAP2 and PCSK6 in the progression of bladder cancer remains unclear, needing to be further investigated." (PMID 36033441, 2022).
cardiac ischemia (1 paper, 2020). "Moreover, the study showed increased secretion of the calcium-dependent serine endoprotease proprotein convertase subtilisin/kexin type 6 (PCSK6), an unexplored protein in cardiac ischemia, from cardiac myocytes by hypoxia." (PMID 32927693, 2020).
colitis (1 paper, 2023). Inflammation of the colon. "After PCSK6 knockdown, the colitis in KO mice was improved relative to WT mice, the TJ protein levels increased, and the proportions of Th1 and M1 macrophages decreased." (PMID 37211384, 2023). "PCSK6 is promising as the new target for the treatment of colitis." (PMID 37211384, 2023). "From our results, after intragastric administration of FITC-D in colitis mice, the serum FITC-D level significantly increased and the permeability elevated, while PCSK6 knockdown reduced the mucosal barrier permeability and serum FITC-D levels." (PMID 37211384, 2023). "PCSK6 binds to STAT1 to promote STAT1 phosphorylation and regulate Th1 cell differentiation, thus promoting the M1 polarization of macrophages and aggravating colitis progression." (PMID 37211384, 2023).
coronary stenosis (1 paper, 2024). Narrowing of the coronary artery lumen diameter. "The regression model showed that carrying the PCSK6 rs1531817 mutant A allele was an independent protective factor against severe coronary stenosis and long-term prognosis in PMI patients." (PMID 39039525, 2024). "The present study is the first to analyse the relationships among PCSK6 polymorphisms, coronary stenosis, and prognosis in patients with PMI from a genetic point of view." (PMID 39039525, 2024). "The PCSK6 rs1531817 mutation A allele was shown to be a protective allele for severe coronary stenosis in patients with PMI in this study." (PMID 39039525, 2024). "This prospective cohort study revealed for the first time that the PCSK6 rs1531817 polymorphism was significantly associated with severe coronary stenosis and long-term prognosis." (PMID 39039525, 2024). "This research aimed to evaluate the relationship of PCSK6 rs1531817 polymorphisms with coronary stenosis and the prognosis in premature myocardial infarction (PMI) patients." (PMID 39039525, 2024). "The mutation at PCSK6 rs1531817 increased the ApoA1/ApoB ratio, which in turn protected against severe coronary stenosis." (PMID 39039525, 2024). "Therefore, the study aimed to evaluate the relationship between PCSK6 rs1531817 polymorphism, coronary stenosis, and the prognosis in PMI patients." (PMID 39039525, 2024). "Finally, this study revealed that the PCSK6 genotype was associated with coronary stenosis and prognosis." (PMID 39039525, 2024). "However, it is still unknown whether the PCSK6 rs1531817 polymorphism is associated with coronary stenosis and the prognosis in PMI patients." (PMID 39039525, 2024). "This study’s results indicate that coronary stenosis and the prognosis of PMI patients are related to the PCSK6 rs1531817 polymorphism, the presence of the PCSK6 rs1531817 mutant A allele is an independent factor associated with the coronary stenosis and prognosis." (PMID 39039525, 2024). "PMI patients with the PCSK6 CA + AA genotype have milder coronary stenosis, partially because they have higher ApoA1/ApoB levels; patients with the PCSK6 CA + AA genotype have a better long-term prognosis, partially because they have lower TC/HDL levels and are less likely to have TVD." (PMID 39039525, 2024). "Additionally, to confirm whether PCSK6 may serve as an interventional target for preventing severe coronary stenosis and improving long-term prognosis, further clinical and basic studies are required." (PMID 39039525, 2024).
end-stage renal disease (1 paper, 2022). "Two of these proprotein convertases have been previously associated with kidney disease: specifically, in the kidney, a high-salt diet induces the PCSK6-corin-ANP-AQP2/β-ENaC pathway suggesting the importance of PCSK6 in renal failure, whereas PCSK7 is linked to end-stage renal disease (ESRD)." (PMID 35045102, 2022).
esophageal cancer (1 paper, 2025). A primary or metastatic malignant neoplasm involving the esophagus. "We observed a significantenrichment of PCSK6, PCSK9,MBTPS1, and FURIN mRNAs in the tumor tissue,which may be indication of the involvement of these PCs in the development andprogression of esophageal cancers." (PMID 40264581, 2025).
esophageal tumors (1 paper, 2025). "Our analysis revealed increased PCSK6,PCSK9, MBTPS1, and FURINexpressions in human esophageal tumors." (PMID 40264581, 2025).
hyperlipidemia (1 paper, 2021). "This is in agreement with the known role of PCSK6 in lipid metabolism, where it cleaves and inactivates endothelial lipase (EL) and lipoprotein lipase (LPL), which can lead to hyperlipidemia." (PMID 35186008, 2021).
idiopathic pulmonary fibrosis (1 paper, 2026). Idiopathic pulmonary fibrosis (IPF) is a nonneoplastic pulmonary disease that is characterized by the formation of scar tissue within the lungs in the absence of any known cause. "A recent genome-wide association study showed that the protease proprotein convertase subtilisin/kexin type 6 (PCSK6) is highly expressed in idiopathic pulmonary fibrosis (IPF) lung parenchyma and that its expression is associated with disease progression and worse survival." (PMID 42278627, 2026).
infarction (1 paper, 2026). A localised pathological necrosis of tissue resulting from obstruction of the blood supply usually by a thrombus, an embolus, or vascular torsion. "Although the functional interaction between Rcn3 and PCSK6 remains to be fully elucidated, these observations raise the possibility that post-infarction proteolytic processing of Rcn3 may influence its anti-fibrotic activity, warranting further investigation." (PMID 41597278, 2026).
lung carcinoma (1 paper, 2013). "These as well as more recent publications demonstrated altered expression of FURIN, PCSK1, PCSK2, and PCSK6 genes in lung cancer." (PMID 23409034, 2013). "At the same time, PCSK6 expression is not necessarily observed in lung cancer, although it is more common in NSCLC than in SCLC." (PMID 23409034, 2013).
male infertility (1 paper, 2018). The inability of the male to effect fertilization of an ovum after a specified period of unprotected intercourse. "CIB1 is related to abnormal spermatogenesis, decreased testis weight and male infertility, while PCSK6 showed a role in female fertility (ovary cysts, increased ovary tumour incidence)." (PMID 29661130, 2018).
membranous nephropathy (1 paper, 2025). "For example, chronic exposure to NSAIDs has been associated with secondary membranous nephropathy, which can present as the nephrotic syndrome associated with the PCSK6 antigen, while penicillamine and mercury exposure have been linked to antibodies against NELL1." (PMID 41441614, 2025). "By employing laser capture microdissection of glomeruli, newer antigens have been identified in nephrotoxin-induced membranous nephropathy and include neural epidermal growth factor-like 1 (NELL1) and proprotein convertase subtilisin/kexin type 6 (PCSK6)." (PMID 41441614, 2025).
metabolic syndrome (1 paper, 2022). A cluster of metabolic risk factors for CARDIOVASCULAR DISEASES and TYPE 2 DIABETES MELLITUS. "In the metabolic syndrome sub-network, five genes had high degrees of connection and could be considered hub genes: PTPRD, DCC Netrin 1 Receptor (DCC), Proprotein Convertase Subtilisin/kexin Type 6 (PCSK6), Unc-13 Homolog C (UNC13C), and Contactin 4 (CNTN4)." (PMID 35121771, 2022).
Myocardial fibrosis (1 paper, 2020). "In a recent paper it was shown that increased levels of PCSK6 in the post-ischemic myocardium lead to reduced ejection fraction due to increased myocardial fibrosis." (PMID 32325687, 2020).
Obesity (1 paper, 2019). Accumulation of substantial excess body fat. "Here, we found that some DMR genes are obesity genes or related to the former which have been studied by genomic and genome-wide association study (GWAS) methods, for example, FTO, PCSK5, PCSK6, NTRK2, ABCC4, TXNIP and RPS6KA2." (PMID 31637123, 2019).
Sepsis (1 paper, 2023). Sepsis is defined as life-threatening organ dysfunction caused by a dysregulated host response to infection. "Our findings showed that PCSK6 played an important role in LPS-induced inflammation and apoptosis in bronchial epithelial cells, which is highly relevant to sepsis-induced ALI." (PMID 37937296, 2023).
cancer (20 papers, 2012 to 2023). A tumor composed of atypical neoplastic, often pleomorphic cells that invade other tissues. "Preliminary data from our research group in teratospermic mice have shown high levels of PCSK6, an indicator of metastasis risk in various types of cancer." (PMID 35406405, 2022). "In fact, PCSK6 was implicated in cancer invasion, a process that resembles trophoblast invasion in many instances." (PMID 28990117, 2018). "In animal cancer models, PCSK6 inhibitors have been shown to inhibit tumor progression, indicating that PCSK6 is a potential cancer target." (PMID 36362216, 2022). "It is suggested that miR-124 depresses prostrate cancer cell multiplication and aggression via proprotein convertase (PC) subtilisin/kexin-6 (PCSK6, also named PACE4) pathway." (PMID 34301174, 2021). "For example, PCSK6, a pro-protein convertase, plays an important role in cancer cell proliferation and ZNF365, a DNA repair pathway gene in the homologous recombination (HR) pathway." (PMID 31681618, 2019). "Several of the top SNPs are in genes associated with PCa or PCa processes, including MKI67 (rs8473), PCSK6 (rs80278342), ABCB6 (rs60322991), and TCHP (rs11068997); or other cancer-associated processes, including GGA2 (rs1135045), H1-5 (rs11970638), and COL15A1 (rs2075662)." (PMID 38052806, 2023). "Considering the shared relation to inflammation, alterations in PCSK6 levels in the case of TGCTs could be a marker as it is in the cancer types mentioned." (PMID 35406405, 2022). "PCSK6: A pro-protein convertase that plays an important role in cancer cell proliferation." (PMID 31681618, 2019). "In cancer tissues, PCSK6 isoforms may differ from those in normal tissues." (PMID 36362216, 2022). "On the other hand, “hub genes” of four other modules contain POU2F3 (↑), CENPH (↑), PCSK6 (↑) and HERC2 (↑), BCAR3 (↑), DOHH (↑), NLK (↑), SCN2A (↑), CACNA2D3 (↓) and CTNND2 (↓), which were commonly reported related to cancer." (PMID 27602771, 2016).
tumor (19 papers, 2010 to 2025). "Studies have implicated PCSK6 in the modulation of cardiovascular function, tumor development, left-right patterning, etc.." (PMID 37937296, 2023). "High tumor-cell expression levels of CP and PCSK6 (from snRNA-seq) are associated with higher tumor grades (FDR < 1e−10; G3 and G4 vs. G1 and G2)." (PMID 36973268, 2023). "Paired basic amino acid cleaving enzyme 4 (PACE4, also known as proprotein convertase subtilisin/kexin type 6 PCSK6) belongs to the family of pro-protein convertases and plays an important role in tumour aggressiveness." (PMID 32781656, 2020). "The genomic aberrations were located in a region of chromosome 1, amplified in one tumor containing Pcsk6, coding for a protease belonging to the pro-protein convertase family." (PMID 20459814, 2010). "Proliferation assays, colony formation assays, cell cycle analysis, migration assays, wound healing assays, Immunofluorescence analysis, and the tumor xenograft model of intrasplenic injection were adopted to evaluate the effects of PCSK6 inactivation on cell growth, migration and liver metastasis." (PMID 36612240, 2022). "To date, PCSK6-mediated cleavage of metalloproteinases, signaling molecules, and apoptotic proteins has been reported as a potential mechanism in tumor invasion and migration." (PMID 36362216, 2022). "PCSK6 is a member of the proprotein convertase family that cleaves and regulates the activity of numerous proteins, suggesting its importance in several physiological and pathological processes like embryogenesis, tumor progression, and cardiovascular diseases." (PMID 37937296, 2023). "Out of 29 candidate genes, proprotein convertase subtilisin/kexin type 6 (PCSK6), was found to be an up-regulated DEG in liver metastasis in this study, and was closely related to tumor progression." (PMID 36612240, 2022). "We found significantly increasedexpressions of the PCSK6, PCSK9,MBTPS1, and FURIN genes in tumor tissue,which may indicate the involvement of these PCs in the formation andprogression of esophageal malignancies." (PMID 40264581, 2025). "We postulated that the inactivation of PCSK6 attenuated the interactions between PACE4 and its substrates, leading to immature growth factors and decreased downstream signaling, mediating the growth of tumor cells." (PMID 36612240, 2022). "CP is a reported tumor marker for ccRCC36–38 but PCSK6 is not." (PMID 36973268, 2023).
cardiovascular diseases (4 papers, 2013 to 2025). "More investigations are anticipated to determine if modulating PCSK6 expression and/or activity is a valid therapeutic strategy for cardiovascular disease." (PMID 36362216, 2022). "Moreover, PCSK6 upregulation plays an important role in macrophage activation in inflammatory and cardiovascular diseases." (PMID 40068774, 2025).
PCSK6 also shares sentences with these, for which no sentence is quoted: non-small cell lung carcinoma (2 papers); prostate adenocarcinoma (2); acute myocardial infarction (1); adenocarcinoma (1); angiosarcoma (1); Aortic dissection (1); asthma (1); autism (1); cardioembolic stroke (1); carotid atherosclerosis (1); Chronic colitis (1); congenital heart disease (1); COVID-19 (1); Ductal carcinomas (1); follicular adenoma (1); genetic diseases (1); Intellectual disability (1); kidney disease (1); Lung Injury (1); lung tumours (1); melanoma (1); ovary tumour (1); papillary carcinoma (1); premature ovarian failure (1); psychiatric disorder (1); renal failure (1); rhinitis (1); schizophrenia (1); skin tumors (1); small cell lung carcinoma (1).
A further 7 diseases each share a sentence with PCSK6 in 1 paper.